PIK3CA (phosphatidylinositol-4,5-bisphosphate 3-kinase catalytic subunit alpha)
Description:
Phosphoinositide-3-kinase (PI3K) phosphorylates phosphatidylinositol (PI) and its phosphorylated derivatives at position 3 of the inositol ring to produce 3-phosphoinositides. Uses ATP and PtdIns(4,5)P2 (phosphatidylinositol 4,5-bisphosphate) to generate phosphatidylinositol 3,4,5-trisphosphate (PIP3). PIP3 plays a key role by recruiting PH domain-containing proteins to the membrane, including AKT1 and PDPK1, activating signaling cascades involved in cell growth, survival, proliferation, motility and morphology. Participates in cellular signaling in response to various growth factors. Involved in the activation of AKT1 upon stimulation by receptor tyrosine kinases ligands such as EGF, insulin, IGF1, VEGFA and PDGF. Involved in signaling via insulin-receptor substrate (IRS) proteins. Essential in endothelial cell migration during vascular development through VEGFA signaling, possibly by regulating RhoA activity. Required for lymphatic vasculature development, possibly by binding to RAS and by activation by EGF and FGF2, but not by PDGF. Regulates invadopodia formation through the PDPK1-AKT1 pathway. Participates in cardiomyogenesis in embryonic stem cells through a AKT1 pathway. Participates in vasculogenesis in embryonic stem cells through PDK1 and protein kinase C pathway. In addition to its lipid kinase activity, it displays a serine-protein kinase activity that results in the autophosphorylation of the p85alpha regulatory subunit as well as phosphorylation of other proteins such as 4EBP1, H-Ras, the IL-3 beta c receptor and possibly others. Plays a role in the positive regulation of phagocytosis and pinocytosis (By similarity).
Synonyms: PI3K-alpha; PI3K; CCM4; CLAPO; CLOVE; CWS5; HMH; MCAP; MCM; MCMTC; p110-alpha
Tractability: Small molecule: an approved drug acts on it; a structure with a bound ligand is known; a high-quality ligand is known; it has a high-quality binding pocket; it belongs to a druggable protein family. Antibody: its Gene Ontology location is reachable by antibodies, with medium confidence. PROTAC: it is named in the literature on targeted protein degradation; ubiquitination databases record sites on it; its protein half-life has been measured; a small molecule that binds it is known.
Target class: Enzyme; Transferase
Chemical probes: ALPELISIB (high quality), APITOLISIB (high quality), CHEMBL2087491, CNX-1351, HS-173, NVP-CRL-457, PD021155, PD080696, PD080779, PD080925, PD081027, PD081265, PD081374, PD081410, PD081454, PD081632, PD081749, PD081803, PD081887, PD081937, and 42 more
Safety:
Unwanted effects reported when the protein is acted on. In parentheses: how it was acted on, where the effect was seen, and who reports it.
drug toxicity (source: ClinPGx)
heart disease (cardiovascular system; source: Force et al. (2011))
No significant results (source: ClinPGx)
Gene: Protein-coding gene on chromosome 3 (179,148,114 to 179,240,093, forward strand). Ensembl gene ENSG00000121879.
Subcellular location (Human Protein Atlas): Cytosol; Primary cilium; Microtubules; Mitochondria
Pathways (Reactome):
Signal Transduction: Activated NTRK2 signals through PI3K; Activated NTRK3 signals through PI3K; Downstream signal transduction; Erythropoietin activates Phosphoinositide-3-kinase (PI3K); Extra-nuclear estrogen signaling; G alpha (q) signalling events; GAB1 signalosome; IRS-mediated signalling; MET activates PI3K/AKT signaling; PI-3K cascade:FGFR1; PI-3K cascade:FGFR2; PI-3K cascade:FGFR3; PI-3K cascade:FGFR4; PI3K Cascade; PI3K events in ERBB2 signaling; PI3K events in ERBB4 signaling; PI3K/AKT activation; PI5P, PP2A and IER3 Regulate PI3K/AKT Signaling; PIP3 activates AKT signaling; RAC1 GTPase cycle; RAC2 GTPase cycle; RAF/MAP kinase cascade; Signaling by ALK; Signaling by LTK; Signaling by SCF-KIT; VEGFA-VEGFR2 Pathway
Disease: Constitutive Signaling by Aberrant PI3K in Cancer; Constitutive Signaling by EGFRvIII; Constitutive Signaling by Ligand-Responsive EGFR Cancer Variants; Signaling by ALK fusions and activated point mutants; Signaling by ERBB2 ECD mutants; Signaling by ERBB2 KD Mutants; Signaling by FGFR1 in disease; Signaling by FGFR2 in disease; Signaling by FGFR3 in disease; Signaling by FGFR4 in disease; Signaling by FLT3 ITD and TKD mutants; Signaling by FLT3 fusion proteins; Signaling by LTK in cancer; Signaling by PDGFRA extracellular domain mutants
and 20 more pathways
Gene Ontology:
Molecular function: 1-phosphatidylinositol-3-kinase activity; 1-phosphatidylinositol-4,5-bisphosphate 3-kinase activity; protein binding; 1-phosphatidylinositol-4-phosphate 3-kinase activity; insulin receptor substrate binding; kinase activity; protein kinase activator activity; protein serine kinase activity; protein serine/threonine kinase activity
Biological process: cellular response to insulin stimulus; interleukin-8-mediated signaling pathway; negative regulation of anoikis; neutrophil chemotaxis; phosphatidylinositol 3-kinase/protein kinase B signal transduction; positive regulation of phosphatidylinositol 3-kinase/protein kinase B signal transduction; positive regulation of protein kinase activity; positive regulation of protein localization to membrane; TORC2 signaling; vascular endothelial growth factor signaling pathway; actin cytoskeleton organization; anoikis; cardiac muscle cell contraction; cardiac muscle contraction; cell migration; cellular response to hydrostatic pressure; endothelial cell migration; epidermal growth factor receptor signaling pathway; insulin receptor signaling pathway; negative regulation of actin filament depolymerization; negative regulation of macroautophagy; phosphatidylinositol phosphate biosynthetic process; phosphatidylinositol-3-phosphate biosynthetic process; phosphatidylinositol-mediated signaling; platelet activation; and 15 more
Cellular component: phosphatidylinositol 3-kinase complex, class IA; cytosol; intercalated disc; perinuclear region of cytoplasm; phosphatidylinositol 3-kinase complex; phosphatidylinositol 3-kinase complex, class IB; plasma membrane; cytoplasm; lamellipodium
Genetic constraint (gnomAD): Loss-of-function variants: 7 observed, 59.46 expected, observed/expected ratio (o/e) 0.12, 90% interval 0.066 to 0.22. The upper end of that interval is the gene's LOEUF score, 0.22, which puts it in group 1 of 6, group 1 being the genes least tolerant of losing a copy. Missense variants: 314 observed, 786.12 expected, observed/expected ratio (o/e) 0.4, 90% interval 0.36 to 0.44. Synonymous variants: 212 observed, 261.24 expected, observed/expected ratio (o/e) 0.81, 90% interval 0.73 to 0.91.
Gene-disease validity (ClinGen):
ClinGen rates the evidence that PIK3CA causes each of these diseases.
hereditary breast carcinoma (autosomal dominant): Refuted. Breast carcinoma that has developed in relatives of patients with history of breast carcinoma.
familial ovarian cancer (autosomal dominant): No Known Disease Relationship. An instance of ovarian cancer that is caused by an inherited modification of the individual's genome.
Cancer hallmarks: proliferative signalling (promotes); angiogenesis (promotes); escaping programmed cell death (promotes); invasion and metastasis (promotes)
Homologues: Orthologues: macaque PIK3CA (100% identical), dog PIK3CA (99% identical), pig PIK3CA (99% identical), rabbit PIK3CA (99% identical), rat Pik3ca (99% identical), mouse Pik3ca (99% identical), guinea pig PIK3CA (96% identical), chimpanzee PIK3CA (95% identical), zebrafish pik3ca (92% identical), tropical clawed frog pik3ca (91% identical), Caenorhabditis elegans piki-1 (22% identical), Drosophila melanogaster Pi3K68D (21% identical). Paralogues in human: PIK3CB (40% identical), PIK3CD (40% identical), PIK3CG (33% identical), PIK3C2B (26% identical), PIK3C2A (25% identical), PIK3C2G (22% identical), PIK3C3 (19% identical), PI4KA (18% identical), PI4KB (13% identical).
Diseases named in the same sentence as PIK3CA in open-access papers:
PIK3CA is named in the same sentence as 609 diseases in open-access papers, as found by Europe PMC text mining. Sharing a sentence is not in itself a finding about the gene and the disease. The quoted sentences say what the papers report.
breast cancer (1,819 papers, 2005 to 2026). A primary or metastatic malignant neoplasm involving the breast. "For example, PIK3CA mutations, commonly observed in breast cancer, were successfully detected in plasma samples with high specificity and sensitivity." (PMID 41602389, 2026). "In breast cancer, this pathway is frequently hyperactivated due to PIK3CA mutations, loss or inactivation of the tumor suppressor PTEN, and hyperactivation of upstream receptor tyrosine kinases (RTKs) such as HER2 and epidermal growth factor receptor (EGFR)." (PMID 41510186, 2026). "PI3Kα inhibitors, particularly alpelisib and inavolisib, combined with endocrine therapy improved progression-free survival in PIK3CA-mutated HR+/HER2- advanced breast cancer, while alpelisib was the only agent to demonstrate an overall survival benefit." (PMID 42052484, 2026). "In the U.S., alpelisib was the first PIK3 inhibitor approved by the FDA for HR+/HER2-advanced breast cancer harboring PIK3CA mutations." (PMID 41496420, 2026). "Between 20 and 50% of breast cancers exhibit PIK3CA mutations, with the most common being hormone receptor positive or HER2 amplified breast cancer." (PMID 41291067, 2026). "Somatic mutation in PIK3CA is another frequent somatic alteration in breast cancer, with a prevalence of up to 40% in ER(+) disease." (PMID 41510186, 2026). "Activating PIK3CA mutations occur in approximately 40% of hormone receptor-positive (HR+)/HER2-negative breast cancers and represent a major driver of endocrine resistance." (PMID 42074235, 2026). "Since E545 is the most common mutation site in the PIK3CA gene, the PIK3CA E545K ctDNA has become a key biomarker for breast cancer." (PMID 41476220, 2026). "Alpelisib, targeting the PI3Kα isoform, provides meaningful benefit in PIK3CA-mutated breast cancer and represents a promising strategy in gynecologic tumors with aberrant PI3K/AKT/mTOR pathway activation." (PMID 42194689, 2026). "It is worth noting that, in current clinical practice, international guidelines recommend a rational use of NGS in advanced breast cancer, prioritizing targeted testing for known actionable mutations (e.g., PIK3CA, BRCA1/2, ESR1, etc.)." (PMID 41018107, 2025). "Among these, PIK3CA, which encodes the p110α subunit, is known as a driver mutation in various cancers, including gastric cancer, breast cancer, ovarian cancer, and lung cancer." (PMID 41008893, 2025). "This is exemplified by PIK3CA mutations in 30%–40% of HR+ breast cancers, driving constitutive PI3K pathway activation and conferring dual resistance to CDK4/6 inhibitors and endocrine therapies." (PMID 40421216, 2025). "PIK3CA mutations are commonly observed in breast cancer, with a particularly high prevalence in HR + subtypes." (PMID 41281644, 2025). "As expected, ER+ breast cancer preclinical models harbouring PIK3CA activating mutations were equally sensitive to PI3Kα (alpelisib) or AKT (capivasertib) inhibition." (PMID 40263319, 2025). "In PIK3CA-mutated HR+/HER2- breast cancer, targeted degradation and inhibition of mutant p110α with inavolisib combined with CDK4/6 inhibition offers a compelling strategy to block both oncogenic signaling and cell-cycle progression." (PMID 41280894, 2025). "Later on, ctDNA has been used in advanced breast cancer to detect PIK3CA mutations as resistance to cyclin kinase inhibitors, and, more recently, for the detection of ESR1 mutations." (PMID 40507825, 2025). "For instance, studies have demonstrated that radiomic features can predict the presence of PIK3CA mutations and other genomic alterations in breast cancer patients." (PMID 40075655, 2025).
breast cancer (continued). "Subsequently, we comprehensively examined all clinical trials that targeted breast cancer patients with PIK3CA mutations." (PMID 40142329, 2025). "Patients with wild-type PIK3CA had better OS (HR 0.161, p = 0.010) and disease-free survival (DFS) (HR 0.376, p = 0.069) than those with PIK3CA mutations in HER2− breast cancer patients." (PMID 40142329, 2025). "For example, inavolisib (GDC-0077), a selective PI3Kα inhibitor, exhibits stronger cytotoxicity in PIK3CA-mutated breast cancer and demonstrates good antitumor effects in animal models." (PMID 41280894, 2025). "Breast cancer with mTOR hyperactivity is often due to PIK3CA mutation which occurs in 20–50% of breast cancers." (PMID 40943615, 2025). "Recently, PI3Kα inhibitor alpelisib was approved in combination with fulvestrant for advanced/metastatic PIK3CA-mutated HR-positive HER2-negative breast cancer in postmenopausal women and men." (PMID 40038309, 2025). "Alpelisib, an orally active inhibitor of the PI3K p110α subunit, has demonstrated efficacy in advanced breast cancer patients harboring PIK3CA mutations." (PMID 40243654, 2025). "For instance, in breast cancer, PIK3CA mutations occur more frequently in White women compared to Black women." (PMID 41187942, 2025). "For instance, in HR-positive breast cancers, PIK3CA mutations are associated with resistance to endocrine therapies such as tamoxifen and aromatase inhibitors." (PMID 40472482, 2025). "This study comprehensively examined all clinical trials involving breast cancer patients with PIK3CA mutations." (PMID 40142329, 2025). "BYL719 (Alpelisib/Piqray) was recently licensed in combination with hormone therapy for PIK3CA-mutated breast cancer." (PMID 40525393, 2025). "The medication is FDA approved for treatment of PIK3CA-mutated advanced breast cancer in combination with fulvestrant." (PMID 40686734, 2025). "Breast cancer cells can develop resistance to lapatinib through several mechanisms, often linked to PIK3CA mutations and PTEN deletions." (PMID 40303296, 2025). "The detection rate of PIK3CA mutation in serum DNA was 22.7% (25/110) in primary breast cancer patients with PIK3CA mutant tumors." (PMID 40055250, 2025). "The PI3Kα inhibitor alpelisib has demonstrated significant clinical benefit when combined with endocrine therapy in patients with HR-positive/HER2-negative advanced breast cancer harboring PIK3CA mutations." (PMID 40909965, 2025). "The prevalence of PIK3CA mutations in countries like Turkey, Tunisia, and Morocco highlights its pivotal role in breast cancer, aligning with global findings." (PMID 40665690, 2025). "Breast cancer cell lines with oncogenic PIK3CA mutations have enhanced sensitivity to RNMT inhibition." (PMID 39869500, 2025). "Among them, PI3Kα plays a particularly well‐characterised role in cancer, especially in breast cancer, where mutations in the PIK3CA gene (encoding PI3Kα) lead to constitutive activation of the pathway." (PMID 40434054, 2025). "Gene mutations in PIK3CA, the catalytic subunit of phosphoinositide 3-kinases, are significantly associated with prognosis in breast cancer." (PMID 40142329, 2025). "PIK3CA mutations are common oncogenic mutations in breast cancer, and abnormal activation of the PI3K/AKT/mTOR pathway is a key mechanism underlying tumorigenesis and drug resistance." (PMID 41280894, 2025). "Studies reveal that patients with HER2-positive breast cancer harboring concurrent mutations in PIK3CA and PTEN exhibit a proclivity towards trastuzumab resistance." (PMID 40303293, 2025).
breast cancer (continued). "In primary ER+ breast cancer, PIK3CA mutations correlate with better outcomes, whereas in the metastatic setting they predict poor prognosis; accordingly, the PI3Kα-selective inhibitor alpelisib is FDA-approved for advanced ER+ breast cancer." (PMID 41226361, 2025). "Studies have shown that mutation in the R172 site can be used to treat patients with HR-positive HER2-negative breast cancer carrying PIK3CA mutation." (PMID 41256322, 2025). "Recurrence of the disease was observed in 47 patients (16.6%), and the postoperative recurrence rate was 13.8% (16/116) and 18.6% (31/167) in patients with PIK3CA mutation and wild-type breast cancer, respectively." (PMID 40472482, 2025). "Among TNBC stage I-III (N = 321) and stage IV (N = 216) breast cancers, the most frequent alterations were mutations in PIK3CA (19.9% vs 21.3%), BRCA1/2 (11.5% vs 12.0%), ESR1 (0.31% vs 0%), PALB2 (0.9% vs 1.4%), and PD-L1 amplification (2.2% vs 4.6%)." (PMID 40421962, 2025). "This study aims to investigate the clinical relevance of plasma-detected PIK3CA mutations in Vietnamese breast cancer patients, with a focus on subtype-specific outcomes." (PMID 41415546, 2025). "Other therapeutic agents against specific gene mutations in breast cancer also target PIK3CA mutations such as alpelisib, trastuzumab, or pertuzumab for HER2-positive cases." (PMID 40665690, 2025). "In HR-positive, HER2-negative breast cancer activate PIK3CA mutations, which enhance PI3Kα kinase activity." (PMID 40665690, 2025). "In breast cancer, approximately 32–37% of all patients with advanced disease harbor a PIK3CA mutation, with the most frequent alterations being p.H1047R (23.1%), p.E545K (23.1%), p.E542K (16.3%), p.H1047L (3.2%) and p.N345K (3.1%, among all PIK3CA mutations)." (PMID 41410746, 2025). "For example, mutations in the p110α subunit (PIK3CA) have been found in around 40% of HR+/HER2− or HER2+ advanced breast cancer tumors." (PMID 40943615, 2025). "Very recently, a research group showed that the genomic features of HRD, PIK3CA mutations with CNAs, and CNAs are enriched in young women with breast cancer." (PMID 40427638, 2025). "Breast cancer patients with PIK3CA mutations demonstrated distinct outcomes compared to PIK3CA wild-type patients." (PMID 40142329, 2025). "PIK3CA mutations are most common in HR-positive breast cancer, and recent data show that treatment-tolerant tumor cells with mutations in the PIK3CA-AKT pathway are more likely to have disease recurrence." (PMID 39929942, 2025). "It has been shown that ER+/HER2− breast cancer patients with PIK3CA mutation exhibited worse survival benefits from KAT6 inhibitor‐based therapy." (PMID 41357671, 2025). "The DFS of breast cancer patients with PIK3CA exon 20 mutation, exon 9 mutation, and wild-type were 22.5-months, 32-months and 24-months, respectively, but the difference was not statistically significant (χ2 = 0.347, p = 0.982)." (PMID 40472482, 2025). "A study of 217 Asian female breast cancer patients demonstrated that PIK3CA mutations were associated with poor prognosis." (PMID 40142329, 2025). "It has been reported that iKnife, a handheld sampling device that uses rapid evaporation ionization mass spectrometry, can detect phosphatidylinositol 3‐kinase (PIK3CA) mutations in real time based on metabolite profiles in breast cancer tissues and cells." (PMID 40552664, 2025). "This association suggests that breast cancer patients with PIK3CA mutations should receive PIK3CA mutant-specific treatment." (PMID 40142329, 2025). "Of the 10 NTRK fusion-positive breast cancer patients, only 1 patient had an additional actionable PIK3CA E545K mutation." (PMID 40385986, 2025). "Liquid biopsy, which is collected through a blood draw, is used in patients with breast cancer to assess DNA mutations in genes such as PIK3CA and ESR1, which have FDA-approved targeted therapeutic interventions." (PMID 40427129, 2025).